ENG (endoglin)
Diseases named in the same sentence as ENG in open-access papers (continued):
Sharing a sentence is not in itself a finding about the gene and the disease.
breast carcinoma (continued). "Firstly, the expression level of endoglin in endothelial cell lines in vitro and mammary tumors in vivo after endoglin silencing was assessed." (PMID 23593103, 2013). "A clear implication of endoglin in cancer is that the plasma level of soluble endoglin appears to correlate with metastasis in patients with breast cancer." (PMID 22069717, 2011). "Previous studies have showed that a high MVD significantly predicts poor survival of breast cancer patients (both relapse-free survival and overall survival) as does a high expression of endoglin." (PMID 19623180, 2009). "Given the increased ENG staining on stromal myofibroblasts in human breast carcinomas, we investigated whether ENG expression is also upregulated in cultured CAFs." (PMID 40644310, 2025). "As CAFs have the ability to promote invasion and metastasis of human breast cancer cells, we sought to determine whether ENG expression on CAFs contributes to their invasion‐ and metastasis‐promoting ability." (PMID 40644310, 2025). "Furthermore, CD105, also known as endoglin, exhibits remarkably high specificity for newly developing neoplastic vessels, making it a useful indicator of angiogenesis and breast cancer metastasis." (PMID 38068422, 2023). "Moreover, ENG overexpression in MDA-MB-231 breast cancer cells impaired migration and invasion, and reduced lung metastasis in vivo." (PMID 33804796, 2021). "Besides the stable human FAP and murine endoglin expressing cells, the breast cancer cell line MDA-MB231 and the wild type of the fibrosarcoma cell line, HT1080, which lack expression of the FAP and murine endoglin proteins were also implemented." (PMID 32316521, 2020). "al. showed that circulating endoglin levels could ameliorate RT-induced late-fibrosis in breast cancer patients by forming stable complex with TGF-β1 and thus diminish the effect of TGF-β1 in inducing tissue fibrosis." (PMID 31500214, 2019). "Furthermore, endoglin, the protein mutated in HHT type 1, has been shown to suppress invasion and metastasis of breast cancer, with lower endoglin expression in the tumour compartment correlating with poorer clinical outcome." (PMID 24354965, 2013). "Various malignant cell types of epithelial origin show an increase in endoglin expression level, including in primary endometrial cancer, head and neck squamous cell carcinoma (especially in tissue samples from metastatic patients), and metastatic breast cancer cells." (PMID 33946583, 2021). "Assessment of endoglin may have other applications in the management of breast cancer." (PMID 17160082, 2006). "Overall, endoglin controls and regulates DEHP-induced SIV sprouting and VEGFA expression in Tg (fli1: EGFP) embryos injected with breast cancer cells." (PMID 35203627, 2022). "Hence, targeting ENG and its downstream signaling pathway might be a promising strategy to normalize vasculature or curb angiogenesis and subsequently inhibit the progression of breast cancer." (PMID 35203627, 2022). "Previous studies have suggested that Hhex regulated cell migration via upregulating ENG expression and downregulating GSC (a critical transcription factor for EMT) expression in breast cancer cells." (PMID 34321041, 2021). "Next to breast cancer models, mice bearing human glioblastoma U87MG (EGFR/CD105+/+) tumors were used to examine the potential of endoglin-based imaging." (PMID 33946583, 2021). "Two years later, the anti-endoglin chimeric antibody TRC105 was conjugated to the NIRF dye IRDye 800CW, and subsequently injected intravenously in 4T1 breast cancer-bearing mice." (PMID 33946583, 2021). "In line with the overexpression results, knocking down Roquin2 increased the mRNA levels of angiogenic genes, including ENG, EDN1, VEGFB, and PDGFC in breast cancer cells." (PMID 34345214, 2021). "The MDA-MB231 xenograft composed of a human breast cancer cell line which lack FAP and murine endoglin expression in vitro." (PMID 32316521, 2020).
breast carcinoma (continued). "Quantification of tumor microvessel density, as determined by immunohistochemical staining for ENG, is a significant indicator of poor prognosis in patients with selected solid neoplasias including NSCLC, cervical cancer, prostate cancer, and breast carcinoma." (PMID 32326402, 2020). "Examples include immunoliposomes targeted to soluble Leishmania antigens, EFGR for glioma, endoglin (CD105), fibroblast activation protein, and HER2 for breast cancer, among others." (PMID 29459867, 2018). "Cell numbers were tested for correlation with serum levels of angiopoietin-2, erythropoietin, endostatin, endoglin, VEGF and sVCAM-1 as well as clinical and pathological features of breast cancer disease." (PMID 16450002, 2006). "Studies have shown that ENG expression is not limited to tumor vessels and increased endoglin expression has been confirmed in some neoplasms including melanoma, leukemias, renal cell carcinoma (RCC), endometrial, ovarian, prostate, breast cancers, and some subtypes of sarcomas." (PMID 39552710, 2024). "Furthermore, in studies of breast cancer, distant metastases were drastically reduced upon simultaneous blockage of angiogenesis through the VEGF inhibitor SU5416 and the endoglin inhibitor TRC105." (PMID 38761292, 2024). "We evaluated the tolerability and preliminary antitumor activity of preoperative letrozole, everolimus, and carotuximab, a monoclonal antibody targeting endoglin, in nonmetastatic breast cancer." (PMID 36735117, 2023). "Historically, the earliest general endoglin-based nuclear imaging study was reported by Fonsatti and coworkers in 2000, by radiolabeling the anti-endoglin monoclonal antibody MAEND3 with 125I and demonstrating specific imaging of breast cancer in a canine model." (PMID 33946583, 2021). "Interestingly, examining expression revealed that in the same luminal A breast cancers INHA, ENG and INHBA are less expressed in responders to pharmacological treatment while TGFBR3 is more expressed in these responder groups." (PMID 33819300, 2021). "Upon encapsulating the liposomes with the NIRF dye DY-676-COOH and conjugation with antibody fragments against endoglin (END-IL), it was shown that NIRF imaging of xenografted human MDA-MB-231 breast cancer cells and HT1080 fibrosarcoma cells was feasible in mice." (PMID 33946583, 2021). "Moreover, ENG stimulates the homing of BM-derived MSCs to different tumor types through TGFβ signaling, including glioma, HCC, and breast cancer." (PMID 33804796, 2021). "In Roquin2-overexpressing MDA-MB-468 and MCF7 cells, we found that proangiogenic factors mRNA, including PDGFC, ENG, EDN1, and VEGFB, were downregulated in two breast cancer cells, while the mRNA expression of antiangiogenic genes, including TIMP1/3, SERPINF1, and ANGPTL4 were upregulated." (PMID 34345214, 2021). "The dense expression of endoglin on blood vessels in highly vascularized tumors led to the study of TRC105 in glioblastoma, renal cell carcinoma (RCC), hepatocellular carcinoma and breast cancer." (PMID 33375670, 2020). "Endoglin (CD105) is highly up-regulated in blood vessels of tissues where neovascularisation occurs, and its expression has been correlated with metastasis in breast cancer and colorectal tumor." (PMID 31195680, 2019). "In a mouse model of HER2/neu-driven breast cancer, the Lm-LLO-CD105A and Lm-LLO-CD105B Lm recombinant vaccines that target endoglin (CD105) expressed in tumor vasculature were able to prevent neovascularization, thereby leading to therapeutic responses against primary and metastatic tumors." (PMID 28588899, 2017). "We observed that ENG suppression by shRNA in myCAFs not only attenuated TGF‐β‐Smad2/3 signaling and TGF‐β1 production but also inhibited the ability of these fibroblasts to promote tumor growth when co‐injected with human breast cancer cells subcutaneously into recipient mice." (PMID 40644310, 2025).
breast carcinoma (continued). "In our cohort, pregnant women with breast cancer treated with chemotherapy during pregnancy show an antiangiogenic state with significantly higher levels of soluble fms-like tyrosine kinase (sFlt-1), sFlt-1/PGF ratio, and soluble endoglin (sEng) at the end of the third trimester." (PMID 33672114, 2021). "Moreover, ENG expression could also differentiate luminal A and HER2+ breast cancers response to taxane therapy." (PMID 33819300, 2021). "Furthermore, in a large breast cancer patient cohort, it was shown that a lack of endoglin expression on tumor cells correlates with a poor clinical outcome." (PMID 32059544, 2020). "However, the breast cancer MVD assessed by endoglin (CD105) does not help to indicate the histopathologic phenotype prone to be referred to anti-angiogenic therapy." (PMID 20953378, 2010). "Consistently, the liposomes accumulated in tumor models originating from human FAP-expressing fibrosarcoma cells and the FAP- and murine endoglin negative breast carcinoma cells at varying levels as could be seen in the differences in fluorescence intensities of the tumors over time post injection." (PMID 32316521, 2020).
endothelial dysfunction (68 papers, 2010 to 2026). In vascular diseases, endothelial dysfunction is a systemic pathological state of the endothelium (the inner lining of blood vessels) and can be broadly defined as an imbalance between vasodilating and vasoconstricting substances produced by (or acting on) the endothelium. "Placental ischemia caused by immune dysregulation causes endothelial dysfunction, increasing antiangiogenic proteins, such as soluble fms-like tyrosine kinase 1 (sFlt-1) and soluble endoglin." (PMID 39394519, 2025). "Another current antiangiogenic marker that has a synergistic effect with sFlt-1 is soluble endoglin (sEng), which is a mediator released from the placenta that causes systemic endothelial dysfunction." (PMID 39590594, 2024). "This triggers the release of anti-angiogenic factors such as soluble fms-like tyrosine kinase-1 (sFlt-1) and soluble endoglin (sEng), causing widespread endothelial dysfunction and systemic inflammation." (PMID 39062815, 2024). "Soluble endoglin (sEng) is associated with inflammation/endothelial dysfunction, and increased sEng levels have been reported in people who do not survive COVID‐19 infection." (PMID 36721385, 2023). "In this study, we identified an association between the endothelial dysfunction marker endoglin and 2-year risk of all-cause death, which was independent of ASCEND-HF score, history of HF, and NT-proBNP." (PMID 34957261, 2021). "Antiangiogenic factors soluble fms-like tyrosine kinase-1 (sFlt-1) and soluble endoglin (sENG) are secreted in excess from the placenta, causing hypertension, endothelial dysfunction, and multiorgan injury." (PMID 29466360, 2018). "Our study shows the emerging role of endoglin as an indicator of diabetes-associated vascular pathologies such as hypertension, endothelial dysfunction and cardiovascular risk." (PMID 21171985, 2010). "This study shows that endoglin is an indicator of hypertension- and diabetes-associated vascular pathologies as endothelial dysfunction and cardiovascular damage." (PMID 21171985, 2010). "Mean serum endoglin levels were nearly doubled in the high-risk group (15.24 ± 4.55 ng/mL) compared to controls (8.42 ± 2.52 ng/mL; t = 9.891, p < 0.001), suggesting its role as a marker of endothelial dysfunction." (PMID 41181724, 2025). "While much more work must be done to fully understand the molecular mechanisms that underlie the role of endoglin in these pathologies, this study provides new research strategies for better diagnosis, prognosis and therapy in diabetes-associated endothelial dysfunction." (PMID 21171985, 2010). "This is the first study in humans showing that plasma Sol-endoglin concentration could serve as an indicator of diabetes-associated pathologies such as hypertension, endothelial dysfunction and cardiovascular risk." (PMID 21171985, 2010). "Abnormal placentation and placental ischemia trigger the release of anti-angiogenic factors such as soluble FMS-like tyrosine kinase-1 (sFLT-1) and soluble endoglin, leading to endothelial dysfunction and platelet activation." (PMID 41939586, 2026). "Soluble endoglin (sENG), a marker of endothelial dysfunction and fibrosis, has been proposed as a non-invasive biomarker of various liver diseases." (PMID 42069951, 2026). "Elevated maternal serum endoglin levels impair vascular remodeling, exacerbate endothelial dysfunction, and are closely correlated with disease onset and severity." (PMID 41181724, 2025). "Human genetics strongly suggests that dysregulated endothelial BMP signalling involving BMP9/ALK1/BMPRII/ENG plays a significant role in endothelial dysfunction and is likely to be the initial trigger for the pathogenesis of PAH43,44." (PMID 41476036, 2025). "This is an interesting finding if we consider the contribution of smoking to endothelial dysfunction, upregulation of matrix metalloproteinases (MMPs) and plaque instability 48, and the role of MMPs in endoglin shedding and elevated sENG levels 12,49." (PMID 40765559, 2025).
endothelial dysfunction (continued). "A crucial factor in the development of PE is inadequate placental invasion, which leads to an excess of placental sFlt-1 and soluble endoglin, which are anti-angiogenic factors that enter the maternal circulation and contribute to endothelial dysfunction." (PMID 40279303, 2025). "The anti-endoglin antibody TRC105 antagonizes endoglin co-receptor activity, ameliorates endothelial dysfunction, and targets pathological angiogenesis, consistent with the context-dependent role of endoglin in EndMT and vascular remodeling." (PMID 41373869, 2025). "Placental endoglin is upregulated in PE, and sEng is released in the maternal circulation; sEng interferes with TGF-β signaling and eNOS activation and thereby causes endothelial dysfunction." (PMID 39063129, 2024). "The increased concentration of endoglin in blood leads to endothelial dysfunction and proliferation." (PMID 37646902, 2023). "On the other hand, CD105, also known as endoglin, has been considered a good marker of endothelial dysfunction in CVD and has been found to be correlated with histological and serum markers of hepatic fibrosis in HCV carriers." (PMID 37373343, 2023). "Endoglin (Eng) is a co-receptor of the transforming growth factor β superfamily playing an important role in endothelial dysfunction." (PMID 36160139, 2022). "Despite the fact that there are several other long-term studies in patients undergoing regular LA therapy, these studies did not provide a long-term evaluation of selected biomarkers of inflammation, endothelial dysfunction, and soluble endoglin." (PMID 33640001, 2021). "This part of the study aimed to evaluate the possible correlation of soluble endoglin with cholesterol and/or with biomarkers of inflammation and endothelial dysfunction." (PMID 33640001, 2021). "The results highlight that endoglin can impede endothelial dysfunction and atherosclerosis and explored the relevant molecular pathways." (PMID 34602076, 2021). "Protein pump inhibitors have been shown in vitro to decrease sFlt‐1 and soluble endoglin and improve markers of endothelial dysfunction." (PMID 33740264, 2021). "We aimed to analyze the data collected in the last 15 years from FH patients treated with LA, to elucidate the benefit of this procedure with respect to plasma lipids, biomarkers of inflammation, and endothelial dysfunction and soluble endoglin." (PMID 33640001, 2021). "Biomarkers of inflammation and endothelial dysfunction were reduced for soluble endoglin, hsCRP, and MCP-1, and sP-selectin after each procedure in some HeFH and HoFH patients." (PMID 33640001, 2021). "It was also demonstrated that high levels of soluble endoglin contribute to the development of arterial hypertension, and when combined with hypercholesterolemia, it can aggravate endothelial dysfunction." (PMID 33640001, 2021). "A clinical study conducted on 288 patients with T2D, hypertension, and healthy controls showed a significant correlation between endoglin and glycemia, glycated hemoglobin, systolic blood pressure, left ventricular hypertrophy and endothelial dysfunction." (PMID 32630452, 2020). "Both reduce placental and endothelial secretion of sFlt-1 and soluble endoglin, and reduce endothelial dysfunction." (PMID 29466360, 2018). "Due to the prominent role of endoglin in endothelial cell signaling and behavior, HHT1 is generally considered a result of endothelial dysfunction." (PMID 29253907, 2017). "The underlying mechanism of HHT1 and HHT2 is haploinsufficiency indicating that reduced amounts of ENG and ACVRL1 lead to endothelial dysfunction and predispose to the clinical signs of disease." (PMID 25763011, 2015). "Lastly, we hope to clarify the prognostic role of the biological markers of endothelial dysfunction such as osteoprotegerin and endoglin, and to standardize their use in clinical practice." (PMID 21524299, 2011).